PRPF6 (pre-mRNA processing factor 6)
Description:
Involved in pre-mRNA splicing as component of the U4/U6-U5 tri-snRNP complex, one of the building blocks of the spliceosome. Enhances dihydrotestosterone-induced transactivation activity of AR, as well as dexamethasone-induced transactivation activity of NR3C1, but does not affect estrogen-induced transactivation.
Synonyms: ANT-1; C20orf14; TOM; bB152O15.1; U5-102K; Prp6; hPrp6; SNRNP102; RP60; ANT1
Tractability: Small molecule: a structure with a bound ligand is known. PROTAC: ubiquitination databases record sites on it; its protein half-life has been measured.
Gene: Protein-coding gene on chromosome 20 (63,981,072 to 64,033,106, forward strand). Ensembl gene ENSG00000101161.
Subcellular location: Nucleus, nucleoplasm; Nucleus speckle
Subcellular location (Human Protein Atlas): Basal body; Nuclear speckles; Nucleoplasm; Centrosome; Cytosol; Vesicles
Pathways (Reactome):
Metabolism of RNA: mRNA Splicing - Major Pathway; mRNA Splicing - Minor Pathway
Disease: Dengue Virus-Host Interactions
Gene Ontology:
Molecular function: identical protein binding; protein binding; protein-macromolecule adaptor activity; ribonucleoprotein complex binding; RNA binding
Biological process: mRNA splicing, via spliceosome; positive regulation of transcription by RNA polymerase II; RNA localization; spliceosomal tri-snRNP complex assembly; RNA splicing; RNA splicing, via transesterification reactions; spliceosomal complex assembly; spliceosomal snRNP assembly; spliceosome conformational change to release U4 (or U4atac) and U1 (or U11); RNA processing
Cellular component: catalytic step 2 spliceosome; membrane; nuclear speck; nucleoplasm; nucleus; precatalytic spliceosome; spliceosomal complex; U12-type precatalytic spliceosome; U2-type precatalytic spliceosome; U4/U6 x U5 tri-snRNP complex; U5 snRNP; U4atac/U6atac x U5 tri-snRNP complex
Genetic constraint (gnomAD): Loss-of-function variants: 42 observed, 121.95 expected, observed/expected ratio (o/e) 0.34, 90% interval 0.27 to 0.44. The upper end of that interval is the gene's LOEUF score, 0.44, which puts it in group 1 of 6, group 1 being the genes least tolerant of losing a copy. Missense variants: 662 observed, 1,299.6 expected, observed/expected ratio (o/e) 0.51, 90% interval 0.48 to 0.54. Synonymous variants: 481 observed, 509.45 expected, observed/expected ratio (o/e) 0.94, 90% interval 0.88 to 1.02.
Homologues: Orthologues: chimpanzee PRPF6 (100% identical), mouse Prpf6 (98% identical), guinea pig PRPF6 (98% identical), dog PRPF6 (98% identical), macaque PRPF6 (97% identical), pig PRPF6 (97% identical), rat Linc00176 (96% identical), tropical clawed frog prpf6 (95% identical), rabbit PRPF6 (95% identical), zebrafish prpf6 (92% identical), Drosophila melanogaster Prp6 (71% identical), Caenorhabditis elegans prp-6 (57% identical), and 1 more. Paralogues in human: CRNKL1 (15% identical), XAB2 (13% identical).